IL4 (interleukin 4)
Diseases named in the same sentence as IL4 in open-access papers (continued):
Sharing a sentence is not in itself a finding about the gene and the disease.
asthma (continued). "The levels of inflammatory cytokines IL‐4 and TNF‐α were increased while IL‐10 and IFN‐γ were decreased in obese asthma; metformin reversed these changes." (PMID 33421348, 2021). "Dupilumab is a IL4/IL13 receptor antagonist, at present approved for the treatment of severe forms of AD, asthma and nasal polyposis." (PMID 35095572, 2021). "IL-4+ γδ T cells, although being expanded in OVA-induced asthma and viral-mediated exacerbation, constitute only a minor subset of total γδ T lymphocytes in mice lungs." (PMID 33661375, 2021). "The level of IL-4 was decreased, but IFN-γ was increased and Th1/Th2 balance was improved in the animal models of asthma treated with AcE and Qt." (PMID 34552650, 2021). "Comparatively, allantoin, another purine metabolite, attenuated lung inflammation (↓eosinophils, lymphocytes and inflammatory cell influx), IgE and Th2 cytokines (IL-4, IL-5) in BALF of ovalbumin-induced lung inflammation in murine models of asthma." (PMID 33919626, 2021). "PBM presents significant and effective results in the reduction of eosinophils, production of IL-4, IL-5, and IL-13 in BAL, airway remodeling, and lung function in asthma." (PMID 35185864, 2021). "The authors reported that there were 15 pathways including IL4 and GATA3-related pathway in the multi-comorbidity of asthma, eczema, and rhinitis, and a number of proteins were obtained potentially related to this multi-comorbidity processes." (PMID 34212158, 2021). "Examination of cytokine profiles from phase 1 demonstrated differences potentially suggestive of an asthma/allergy phenotype in mothers of ASD children, with elevated concentrations of IFN-γ, IL-4 and IL-5." (PMID 33736683, 2021). "In ACO mice, there was an overlap of asthma and COPD with marked increases of total leukocytes, neutrophils, and eosinophils counts and higher levels of inflammatory cytokines (IL-4, IL-6, TNF-α, IL-1β, IL-17A, and IFN-γ) in BALF." (PMID 33869177, 2021). "Individuals with CF and/or asthma are typically diagnosed with ABPA and exhibit a type 2 immune response that leads to the production of high levels of interleukin 4 (IL-4), airway eosinophilia, and increased total and A. fumigatus-specific IgE." (PMID 33597172, 2021). "TNF-α, IL-13, IL-4, IL-17A and CCL2 are found to increase RhoA mRNA expression via NF-κβ and STAT6 signaling pathways activation, leading to airway hyperreactivity in asthma." (PMID 34069141, 2021). "Treatment of the asthmatic rats with evodiamine prevented this increase, with IL-4, IL-13, and IL-17 levels in BALF, relative to the asthma group." (PMID 33577738, 2021). "There are now two agents which bind IL5 (mepolizumab, reslizumab), an anti-IL5 receptor antagonist (benralizumab), and more recently an anti-IL4 a receptor antagonist which blocks IL4 and IL13 signalling (dupilumab) approved for the treatment of asthma." (PMID 33860282, 2021). "Because Th2 cytokines, including IL-13 and IL-4, act on goblet cell hyperplasia, fibroblast-to-myofibroblast transformation, collagen deposition, and airway smooth muscle contraction, high FeNO levels in patients with severe asthma may be affected by airway remodeling." (PMID 35008504, 2021). "In T2-high asthma, CD4+T helper 2 (Th2) cells and innate lymphoid cells group 2 (ILC2), eosinophils, immunoglobulin E (IgE) and T2 cytokines such as interleukin (IL)-4, IL-5 and IL-13 contribute to its pathogenesis." (PMID 34777398, 2021). "Our study concluded that IL-4 is a potential target for preventing infection-induced AHR and severe asthma." (PMID 34226412, 2021). "Higher serum levels of TNF-α, IL-13, IL-4, IL-10, hs-CRP and FeNO were determined in asthma patients than in healthy volunteers (P<0.05)." (PMID 33223504, 2020). "Western blot analysis results of lung tissues showed that in Tespa1−/− asthma mice, the phosphorylation level of JAK1 increased, but the increase in P-JAK2 level was negligible, indicating that Tespa1 mainly regulates the IL-4/JAK1 signaling pathway." (PMID 33228696, 2020).
asthma (continued). "Recent investigations have shown IL-4 increased in serum, bronchoalveolar lavage fluid (BALF), and sputum in asthma patients and animal models, as well as different asthma phenotypes, as rhinitis, severity or atopy." (PMID 32366038, 2020). "Hence, additional studies are needed to further characterize the cellular phenotypes of dual Th2/Th17 lymphocyte subsets, and to better understand if IL-4 and IL-17 produced by these cells could eventually exert additive or synergistic effects, especially in the pathobiology of severe asthma." (PMID 33329598, 2020). "Accordingly, we observed that the gene expression of both IL4 and IL13 were significantly upregulated in the lungs of human asthma patients as compared to those from healthy donors." (PMID 32477356, 2020). "The results showed that the number of IL-4+ T cells and IFN-γ+ T cells increased in the asthma model." (PMID 32489402, 2020). "The result showed that the number of IL-4+ T cells and IFN-γ+ T cells in the asthma model group was significantly higher than that in the control group (P < 0.0001, P < 0.01)." (PMID 32489402, 2020). "The expression of PRMT1 was cell type specific and responded to several well-known asthma triggers including TGF-β1 and IL-4." (PMID 31979396, 2020). "As we all know, molecules such as IL-4, IL-6, TNF-α, Ig-E, and Th17cell played key roles in the pathological process of asthma." (PMID 32831980, 2020). "The use of Nigella sativa resulted in an improvement in asthma control and PEF, which was accompanied by a reduction in eosinophils numbers in blood, an increase of IFN-γ and an increase in IL-4." (PMID 33339167, 2020). "For example, TMEM16A was found to be expressed in airway epithelium stimulated with IL-4/IL-13, and plays an important role in mucus secretion in patients with COPD and asthma." (PMID 32514271, 2020). "The renowned type-2-high immunity occurs in almost half of asthma patients, manifested as features of eosinophilia, AHR, the elevation of IL-4, IL-5, IL-13, and Ig E in lung and blood." (PMID 33013383, 2020). "Inhibiting the biological effects of both IL4 and IL13 with the monoclonal antibody dupilumab has been shown to markedly decrease asthma exacerbations and improve lung function." (PMID 33506093, 2020). "You22 detected some cytokines in bronchoalveolar lavage fluid (BALF) in asthma model, and OVA and DEHP participated a salient Th2 response which was characterized by the upregulation of Th2-type cytokines, such as IL-4, IL-5 and IL-13." (PMID 32884073, 2020). "An earlier study also reported that fucoidans isolated from U. pinnatifida sporophylls attenuated the Th2 response via suppressing Th2 cytokines (IL-4, IL-5, IL-13) in an OVA-induced mouse model of asthma." (PMID 32580518, 2020). "The serum IFN-γ, IL-4 and LTB4 levels in asthma guinea pig induced by histamine and OVA (mean ± SD, n = 8)." (PMID 31531069, 2019). "In allergic disease such as asthma and allergic rhinitis, interferon gamma/interleukin 4 (IFN-γ/IL-4) cytokines or Th1/Th2 balance shifted toward IL-4 or Th2 lymphocyte." (PMID 31156785, 2019). "Higher levels of several Th2 cytokines have been found in BAL of asthmatics, including IL-4, IL-5, IL-13, IL-25, IL-33, and TSLP, and the levels of Th2 cytokines correlate with severity of asthma exacerbation." (PMID 30764493, 2019). "The antiasthma simplified herbal medicine intervention (ASHMI) alleviates asthma symptoms by modulating Group 1 cytokine (inhibition of TNF-α and IL-6) and Group 2 cytokine (inhibition of IL-17, IL-13, IL-5, and IL-4, and enhancement of IFN-γ) expression." (PMID 31284537, 2019). "Overall, these observations indicated that OVA DNTs selectively homed in to lung/lung-related tissues and suppressed IL-4, IL-21, and OVA-specific antibody production in an OVA-induced asthma model." (PMID 31534137, 2019).
asthma (continued). "“Immune System” was a heterogenous group of molecular processes such as dendritic cell chemotaxis and cytokine production, IL-1, IL-3, IL-4, TLR and PD-1 signaling, asthma-related signaling and activation of RAS GTPase in B-cells." (PMID 31597351, 2019). "Intriguingly, recent studies suggest that IL4 can induce autophagy in activated CD4+ Th2 cells, primary dendritic cells (DCs), and primary B cells that exacerbates experimental asthma through different mechanisms." (PMID 31849968, 2019). "Pathway cross-talk analysis highlights that signaling pathways mediated by IL-4/13 and transcription factor HIF-1α and FOXA1 play crucial roles in the pathogenesis of asthma." (PMID 31430856, 2019). "In analyses of asthma and allergy, we observed lower DNAm of several CpGs in genes regulating eosinophilic and Th2 responses: EPX and IL-4, respectively." (PMID 31300640, 2019). "The results indicated that Pheretima aspergillum can inhibit infiltration and diffusion of inflammatory cells in asthma model guinea pigs, and regulate IFN-γ, IL-4, and LTB4 secretions." (PMID 31531069, 2019). "In asthma, the paradigm of allergic disease, the cytokine profile in BAL shows elevation of IL-4, IL-5, and IL-9 compared to control groups." (PMID 31772507, 2019). "Functional gene categories represented in DMRs and individual CpGs found for FeNO, asthma, and allergy were eosinophilic activity (EPX, CLC, PRG2), and Th2 responses (IL-4, ZFPM1)." (PMID 31300640, 2019). "Nevertheless, these data appear contradictory to previous reports suggesting that TMEM16A plays a key role in mucus production, namely, in asthma where both TMEM16A and MUC5AC are concomitantly up-regulated by IL-4 or IL-13 induction." (PMID 31732694, 2019). "In order to test the RbLoTem protective activity and their dependence on IL-4 in vivo, we performed an adoptive transfer experiment into a house dust mite (HDM)-induced acute asthma model." (PMID 31120919, 2019). "The precursors of ASHMI, MSSM-002, inhibit Group 2 cytokines (the inhibition of IL-4, IL-5, IL-13, and GATA-2 and the enhancement of IFN-γ expression) to relieve asthma symptoms." (PMID 31284537, 2019). "A birth cohort study has shown the association of prenatal cytokine production (cord-blood concentrations of IL-4, IFN-γ, and tumor necrosis factor) with the development of atopy and asthma at 6 years of age." (PMID 31507589, 2019). "When considering the pathophysiology of respiratory diseases such as asthma or COPD, interleukins, especially IL-4, IL-13, IL-1β, and IL-17, are the major inflammatory instigators." (PMID 30744098, 2019). "Furthermore, the expression of serum IL-1β, IL-4 and IL-17F was higher in the asthmatic model compared to those being transplanted by mASCs, indicating that cell therapy might improve the degree of asthma airway inflammation and airway remodeling through regulating the Th1/Th2 ratio." (PMID 30089474, 2018). "The increased serum IL-4 levels and elevated expression of GATA3 in patients with asthma confirmed a deviation toward Th2 cells in patients with asthma that play a prominent role in pathogenesis of allergic asthma." (PMID 30116273, 2018). "The serum levels of IL-4, the expression level of GATA3, and GATA3/FOXP3 ratio in patients with asthma were significantly higher than healthy subjects (P <0.002, P <0.001, and P <0.004, respectively)." (PMID 30116273, 2018). "Although these inhibitors have shown minimal benefits for asthma in clinical trials, knocking-out all of the NOS isoforms decreases airway inflammation and reduces Th2 cytokines such as IL-4, IL-5, and IL-13 in asthmatic mice." (PMID 29302700, 2018). "The OX40L, IL-4 and IL-17 in patients with acute episode of asthma were increased in comparison with patients with stable asthma or healthy control, OX40L, IL-4 and IL-17 in patients with stable asthma were increased in comparison with healthy control." (PMID 29554934, 2018).
asthma (continued). "Both IL4 and IL13 were important in asthma pathology, typically in those patients with Th2 profile inflammation." (PMID 29751569, 2018). "The results of the current study indicated that the serum level of IL-4 and GATA3 expression were significantly higher in patients with asthma compared with the healthy individuals." (PMID 30116273, 2018). "In the dexa/hypergravity group, IL-4, IL-5 and IL-13 secretion in the BAL fluid decreased statistically significantly (p < 0.001) compared with the asthma group." (PMID 29772010, 2018). "The CD4+ T cell is a dominant activated T cell subtype in clinical allergic asthma and in animal models of asthma, an mainly contributes to AHR development and allergic inflammation by secreting Th2 cytokines such as IL-4, IL-5, and IL-13." (PMID 29910732, 2018). "Asthma is characterized by an expansion of CD4+ helper T lymphocytes (Th2, Th17), increased production of the Th2 cytokines IL-4, IL-5, and IL-13, an increased level of allergen-specific immunoglobulin E (IgE), eosinophilia and inflammation of the airways." (PMID 30622536, 2018). "Th2 cells can increase the secretion of Interleukin-4 (IL-4) and antagonize the emergence of Th1 cells including interferon-γ (IFN-γ) and hence further promote the development of asthma." (PMID 29554934, 2018). "We found that the frequencies of GATA3+IL-4+, GATA3+IL-5+, and GATA3+IL-13+ CD4+ T-cells in the lungs of asthma-induced Bcl11bfl/fl dLck-iCre mice were reduced, as were the frequencies of GATA3+, IL-4+, IL5+, and IL-13+ CD4+ T-cells." (PMID 29700302, 2018). "In both groups of healthy subjects and patients with asthma, TGF-β and IL-4 production by PHA-stimulated PBMCs were significantly higher than those of the unstimulated cells (P <0.05 and P <0.001, respectively)." (PMID 30116273, 2018). "In mild and moderate asthma, the T helper type 2 (Th2) cells dominated over the T cell lineage in the airway, which were the producers of the typeII cytokines IL4 and IL13, which had a high message and protein level in asthma patients." (PMID 29751569, 2018). "In murine models of asthma, CD4+ T-helper cells in the lungs and bronchoalveolar lavage fluid decrease eosinophilia and the Th2 cytokine secretion of IL-4, IL-5, IL-13, and TGF-β." (PMID 29959403, 2018). "The concentrations of IFN-γ, IL-4, IL-5, IL-10 and IL-17 in BALF were therefore determined, to confirm the establishment of the mouse asthma model at the molecular level." (PMID 28931832, 2017). "Conversely, in severe asthma with CRS, Th2-derived cytokines of IL-4, IL-5, and IL-13 were markedly expressed in the epithelium, endothelium, subepithelial infiltrating cells, and mucus glands (respectively)." (PMID 28199345, 2017). "IL-4 level is elevated in ILD and asthma lung biopsies and in peripheral blood and synovial fluid in early RA." (PMID 28720095, 2017). "Intranasal siRNA nanoparticles targeting c-kit reduced infiltration of eosinophils in BAL fluid, downregulated the production of SCF, IL-4, and IL-5, and suppressed airway mucus secretion in an OVA-induced mouse asthma model." (PMID 28106744, 2017). "The results showed that treating asthma mice with TT significantly suppressed the levels of IL-4 and IL-13, and increased the IFN-γγ levels in the BALF, as compared with the data of asthma mice treated with ST." (PMID 28769099, 2017). "For the analyzes of the IL-4, IL-5 IL-10 and IFN-γ cytokines in the BAL supernatant–the cytokines related to the mechanism (Th2) of asthma were evaluated in the BAL supernatant." (PMID 29145431, 2017). "In animals treated with dexamethasone, gene expression of IL-4 (p < 0.05), IL-17 and TGF-β (p < 0.001 for both cases) were significantly reduced compared with untreated asthma group." (PMID 28824424, 2017).
asthma (continued). "In particular, Doganci and colleagues found that local blockade of the sIL-6R in an ovalbumin mouse model of the late-phase asthma response reduced eosinophil numbers in BALF and decreased levels of the Th2 cytokines IL-4, IL-5, and IL-13." (PMID 28334838, 2017). "siRNAs targeting IL-4 and respiratory syncytial virus (RSV) simultaneously were studied in a mouse model of virus-induced asthma exacerbation." (PMID 28106744, 2017). "Higher expression of Th2-driven cytokines (IL-4, IL-5, IL-9, and IL-13), TSLP, IL-25 and IL-33 in nasal tissues was observed in severe asthma." (PMID 28199345, 2017). "The effect of Z. multiflora on cytokines of human lymphocytes and lung lavage of guinea pigs model of asthma showed reduced IL-4 and enhanced IFN-γ gene expression as well as increased IFN-γ/IL-4 ratio which support the findings of the present study." (PMID 28824424, 2017). "Serum IFN-γ, IL-4, and IL-17A levels were increased in RSV and asthma mice compared with control mice while IL-10 levels were decreased." (PMID 29123203, 2017). "PedsQL3.0 was used to measure the effect of asthma on QOL of children, and the correlation between IL-4, IL-6, and IL-12 levels and the lung function and QOL was measured." (PMID 28328807, 2017). "Concurrently, levels of IFN-γ, IL-4, and IL-17A in serum, lung tissues, and BALF increased in RSV-infected asthma mice while levels of IL-10 declined." (PMID 29123203, 2017). "Therefore, IL-4 and IL-13 may be key factors in suppressing the induction of asthma." (PMID 29151835, 2017). "Daily oral administration of WGP (400 μg) significantly reduced pulmonary eosinophil influx and production of Th2 cytokines (IL-4, IL-5, IL-13), however serum IgE levels were unaffected by WGP treatment in an OVA-induced asthma model." (PMID 27390655, 2016). "According to the results, IL-4 and TNF-α of asthma mice were increased, compared with the blank control group (P < 0.05), suggesting that IL-4 and TNF-α participate in the onset of asthma." (PMID 27143988, 2016). "The serum samples of these mice also had lower IL-1β (all P < 0.05), TNF-α (all P < 0.05), IL-4 (all P < 0.05) and IL-5 (all P < 0.05) levels and higher levels of IFN-γ (P < 0.001) compared with the OVA-induced asthma mouse model." (PMID 27134644, 2016). "It is well known that inflammatory mediators such as IL-4 and IL-13 as well as the persistence of chronic inflammation in airways are involved in the remodeling process, so natural compounds that inhibit the inflammatory process in asthma may also prevent the remodeling process." (PMID 27445433, 2016). "Our data demonstrating reduced IL-4 and IL-5 levels in WGP-treated mice in an OVA-induced asthma model is in agreement with these findings." (PMID 27390655, 2016). "Pharmacological therapies using specific receptors IL-4, IL-5, TNF and IL-1β blockers are likely to constitute a considerable development in asthma management." (PMID 27536321, 2016). "Airway inflammation is a key component of asthma and of the OVA-sensitization model and is characterized by the presence of granulocytes and increased levels of Th2 cytokines such as IL13, IL4 and IL5." (PMID 27820848, 2016). "The expression levels of the classical inflammatory biomarkers such as IgG, IgE, MMP9, IFN-γ, IL-4, and ICAM-1 that play an important role in the pathogenesis of asthma were also assessed." (PMID 28050193, 2016). "According to our results, P2Y6 increased IL-4 release during the process of asthma and the function of P2Y6 on IL-4 should be actively studied." (PMID 27590515, 2016). "The population of IL-4+ Th2 cells increased from 0.329% in PBS group to 0.736% in asthma group and 0.796% in severe asthma group, while recombinant Mycobacterium smegmatis vaccination significantly reduced IL-4+ Th2 cells in spleen." (PMID 26974537, 2016). "Knockdown of the Notch l gene by small interfering RNA led to overproduction of IL-4 and IFN-γ, which played an important role in the pathogenesis of asthma." (PMID 26339131, 2015).